KMT5B (lysine methyltransferase 5B)
Diseases named in the same sentence as KMT5B in open-access papers:
KMT5B is named in the same sentence as 44 diseases in open-access papers, as found by Europe PMC text mining. Sharing a sentence is not in itself a finding about the gene and the disease. The quoted sentences say what the papers report.
glioblastoma (8 papers, 2021 to 2026). The most malignant astrocytic tumor (WHO grade IV). "Conversely, KMT5B dysregulation is associated with diverse pathologies: deficiency is linked to glioblastoma, sarcoma, and neurodevelopmental disorders, whereas overexpression correlates with hepatocellular carcinoma and chronic myelogenous leukemia." (PMID 42080071, 2026). "Our analysis revealed that KMT5B was associated with significantly shorter survival in glioblastoma, which requires further research and validation." (PMID 36998447, 2023). "Two inactivating mutations of KMT5B (R187* and R699*) were identified in glioblastoma and diffuse intrinsic pontine glioma (DIPG) samples, which abrogated DNA repair and increased invasion and migration in neighboring cells." (PMID 37214395, 2023). "Previous studies have shown that KMT5B overexpression reduces the proliferation of glioblastoma cells, and enhanced activity of KMT5B can suppress VEFGR2 expression in endothelial cells." (PMID 38877400, 2024). "Ectopic overexpression of KMT5B induced tumor suppressor-like features in vitro and in a mouse tumor xenograft model, as well as changes in the expression of several glioblastoma-related genes." (PMID 34447744, 2021). "Furthermore, in glioblastoma (GBM), the nuclear expression levels of lysine methyltransferases, such as SETDB1, KMT5B, Suv-39h1, and EZH2, are elevated and associated with advanced histological cancer grades." (PMID 39620228, 2024). "The alterations in FGFR4, KIT, and PEG3 were correlated with a short OS in astrocytoma, alterations in CDK4, FUBP1, and NTRK2 were correlated with a short OS in oligodendroglioma, and alterations in CDK4, CIC, FGFR3, and KMT5B were correlated with a short OS in glioblastoma." (PMID 36998447, 2023). "Additionally, we conducted pairwise correlation analyses between KMT5B and candidate genes using the cBioPortal platform with microarray data obtained from the comprehensive characterization of glioblastoma performed by the TCGA consortium." (PMID 34447744, 2021).
autism spectrum disorder (5 papers, 2022 to 2025). A spectrum of developmental disorders that includes autism, and Asperger syndrome. "Pathogenic dominant variants in KMT5B have been associated with neurodevelopmental disorders, intellectual disability, autism spectrum disorder, and, in some cases, overgrowth phenotypes." (PMID 41464539, 2025). "Heterozygous mutations in KMT5B, including missense, nonsense, and deletion variants, have been linked to a variety of phenotypes, ranging from developmental delay and autism spectrum disorders to more severe intellectual disability (MIM: 617788)." (PMID 41464539, 2025). "Recently, deleterious heterozygous variants in KMT5B were implicated in individuals with intellectual disability (ID) and/or autism spectrum disorder." (PMID 35433545, 2022). "Lysine Methyltransferase 5B (KMT5B), a methyltransferase targeting histone H3K4, promotes transcriptional activation and has been implicated as a risk gene in autism spectrum disorders." (PMID 40417780, 2025). "Most recently, heterozygous disease-causing variants in the Lysine Methyltransferase 5B (KMT5B) gene, have been described in individuals with neurodevelopmental delay, with or without seizures and/or autism spectrum disorder (ASD) (MIM #617788)." (PMID 35433545, 2022).
autism (4 papers, 2016 to 2024). Persistent deficits in social interaction and communication and interaction as well as a markedly restricted repertoire of activity and interest as well as repetitive patterns of behavior. "Clinical studies have shown that pathogenic variants of KMT5B are associated with global developmental delay, macrocephaly, autism, and congenital abnormalities (OMIM# 617788)." (PMID 38637503, 2024). "Similar to CHD8, the single parent carrying KMT5B LGD mutations also shows a lower IQ within normal range and features consistent with a broader autism phenotype." (PMID 30564305, 2018).
developmental delay (3 papers, 2021 to 2025). "They described seven patients with NDD, mainly global developmental delay (GDD) and autism spectrum disorder (ASD), who carried both missense and likely gene disruptive (LGD) variants in KMT5B, mostly de novo in origin." (PMID 41153391, 2025).
glioma (3 papers, 2023 to 2024). A benign or malignant brain and spinal cord tumor that arises from glial cells (astrocytes, oligodendrocytes, ependymal cells). "Considering their significantly shorter overall survivals and the anti-tumoral effect of KMT5B, it could be suspected that this deletion–insertion in the C-terminal region may cause functional defect to KMT5B and de-repression of oncogenes in a subgroup of adult patients with pediatric-type glioma." (PMID 37214395, 2023). "The alterations of CDKN2B, KMT5B, MAP2K1, PIK3CA, and chr9p were associated with hemorrhage, and this may be due to the fact that most of them affect glioma cell proliferation and invasion." (PMID 38877400, 2024). "Notably, 5 of 6 patients with altered KMT5B in our study had the same mutation of p.Glu833_Asp835delinsSerProSer, including 3 diffuse astrocytomas, MYB- or MYBL1-altered and 2 diffuse pediatric-type high-grade gliomas, H3-wildtype and IDH-wildtype." (PMID 37214395, 2023).
Macrocephaly (2 papers, 2022 to 2025). Occipitofrontal (head) circumference greater than 97th centile compared to appropriate, age matched, sex-matched normal standards. "While macrocephaly and/or overgrowth were not consistently described among patients with KMT5B variants, we suggest that this genetic diagnosis should be entertained in undiagnosed patients with ID and macrocephaly or overgrowth." (PMID 35433545, 2022).
Obesity (2 papers, 2023 to 2024). Accumulation of substantial excess body fat. "In obesity, KMT5B and KMT5C regulate metabolism through downregulating peroxisome proliferator activator receptor gamma (PPAR-γ), which regulates lipid storage and glucose metabolism." (PMID 37671044, 2023). "While the data from this work suggest that KMT5B/C proteins may be a therapeutic target for the treatment of obesity, other reports suggest a contradictory effect with regards to KMT5C in obesity, more specifically in adipocytes." (PMID 37671044, 2023).
sarcoma (2 papers, 2022 to 2026). A usually aggressive malignant neoplasm of the soft tissue or bone. "Analysis of TCGA data revealed that human sarcomas are characterized by reduced expression levels of KMT5B due to copy number loss and DNA hyper-methylation." (PMID 36376321, 2022). "Low KMT5B expression is prevalent in human sarcomas and associated with tumor recurrence, suggesting a common function of KMT5B in sarcoma formation." (PMID 36376321, 2022). "In conclusion, copy number loss combined with DNA hyper-methylation of promoter regions appears to contribute to inhibition of KMT5B expression in human sarcomas." (PMID 36376321, 2022). "The low expression of KMT5B in sarcomas may be attributed to structural abnormalities of q13 on chromosome 1135,44,45 as indicated by alterations of KMT5B copy numbers." (PMID 36376321, 2022). "The lower disease-free interval of sarcoma patients with reduced expression of KMT5B compared to patients with higher KMT5B levels suggest that KMT5B level might be a usefull prognostic marker." (PMID 36376321, 2022). "Moreover, the promoter region of KMT5B (cg1766288, cg2010049) is much more methylated in sarcomas compared to carcinomas such as THCA, PRAD, LUAD and BRCA, probably accounting for transcriptional repression of KMT5B." (PMID 36376321, 2022). "To analyze whether KMT5B plays a role in the formation of human sarcomas, we examined the TCGA pan-cancer data set and detected a significantly lower expression of KMT5B in sarcomas than in most other malignancies." (PMID 36376321, 2022).
hemorrhage (1 paper, 2024). Loss of blood from the vascular compartment to the exterior or into nonvascular body space as a result of rupture or severance of the blood vessels. "CDKN2B, KMT5B, and PIK3CA alterations were common in the hemorrhage group, suggesting a possible mechanism for the prognostic value of intratumoral hemorrhage." (PMID 38877400, 2024). "Molecular analysis indicated that CDKN2B, KMT5B, and PIK3CA alteration occurred more in the hemorrhage group (CDKN2B, 84.4% vs. 62.2%, p = 0.029; KMT5B, 25.0% vs. 8.9%, p = 0.029; and PIK3CA, 81.3% vs. 58.5%, p = 0.029)." (PMID 38877400, 2024).
leukemia (1 paper, 2024). A malignant (clonal) hematologic disorder, involving hematopoietic stem cells and characterized by the presence of primitive or atypical myeloid or lymphoid cells in the bone marrow and the blood. "The new frontier in the field will be the assessment of the impact of somatic polymorphism on leukemia risk; we previously identified a significant risk locus for leukemia at 11q13.2 (rs4930561; KMT5B), and there is increasing evidence of germline predisposition to clonal hematopoiesis." (PMID 39135995, 2024).
malignant glioma (1 paper, 2021). A grade III or grade IV glioma arising from the central nervous system. "Interestingly, it also highlighted the association of certain other genes with both malignant glioma and kidney diseases, thus pointing to a yet-undescribed hypothetical role of KMT5B in such renal pathologies." (PMID 34447744, 2021).
muscular dystrophy (1 paper, 2019). Muscular dystrophy (MD) refers to a group of more than 30 genetic diseases characterized by progressive weakness and degeneration of the skeletal muscles that control movement. "The role of Kmt5b in muscle differentiation has been further verified in cell line and disease models of muscular dystrophy, where mice with even a partial muscle-specific knockout of Kmt5b display centrally nucleated myofibers and necrosis." (PMID 30832413, 2019).
myelodysplastic syndrome (1 paper, 2021). A clonal hematopoietic disorder characterized by dysplasia and ineffective hematopoiesis in one or more of the hematopoietic cell lines. "KMT5B is implicated in AML pathogenesis where mutation has been associated with transformation from precursor myelodysplastic syndrome to AML16." (PMID 34716350, 2021).
myeloid neoplasm (1 paper, 2023). Proliferation of myeloid cells originating from a primitive stem cell. "Other histone methylating genes, such as KMT5B/EZH1/KMT2D/KMT2E/SETD5, were also included in brown module, and related to pathological process or prognosis of myeloid neoplasms (MDS/AML)." (PMID 37953918, 2023).
overgrowth syndrome (1 paper, 2022). A group of syndromes caused by genetic birth defects that may lead to the development of malignancies. "Further, some have even suggested a KMT5B-associated overgrowth syndrome including tall stature and macrocephaly in these patients." (PMID 36035149, 2022).
rhabdomyosarcoma (1 paper, 2022). A rare aggressive malignant mesenchymal neoplasm arising from skeletal muscle.
cancer (12 papers, 2014 to 2026). A tumor composed of atypical neoplastic, often pleomorphic cells that invade other tissues. "We found that low expression of KMT5B is associated with a shorter disease-free interval in all 29 cancer types analyzed, suggesting that KMT5B plays a role in cancer progression and recurrence." (PMID 36376321, 2022). "Loss of Kmt5b provoked collision-associated R-loop formation on various cancer driver genes and activated pro-tumorigenic signaling in MuSCs, but no malignant transformation of Kmt5bsKO MuSCs occurred." (PMID 36376321, 2022). "KMT5B (SUV420H1) encodes a lysine methyltransferase that is frequently mutated in human cancers, with gene amplifications being particularly common." (PMID 34716350, 2021). "H4K20me2 enrichment was found immediately upstream of the promoter regions of a subset of deregulated genes, thus suggesting a possible role for KMT5B in GBM through the epigenetic modulation of key target cancer genes." (PMID 34447744, 2021). "Further, changes in H4K20 methylation and KMT5B expression in human cancers also support a link to maintenance of cell “stemness”, as cancer cells often de-differentiate during transformation to gain motility and the ability to divide at will." (PMID 30832413, 2019). "This review summarizes the biological functions and pathological roles of KMT5B identified over the past decades, highlighting its potential as a therapeutic target for both cancer and non-cancer diseases." (PMID 42080071, 2026).
neurodevelopmental disorder (7 papers, 2022 to 2026). A behavioral and cognitive disorder with onset during the developmental period that involves impaired or aberrant development of intellectual, motor, or social functions. "Autosomal dominant intellectual developmental disorder 51 (#MIM 617788) is a complex neurodevelopmental disorder (NDD) caused by pathogenic variants in the lysine methyltransferase 5B gene (KMT5B)." (PMID 41153391, 2025). "Pathogenic variants in KMT5B, a histone lysine methyltransferase, have been linked to neurodevelopmental disorders, yet their effects on human skeletal muscle remain unexplored." (PMID 41464539, 2025). "Here, we report on a male patient with a severe neurodevelopmental disorder caused by a novel KMT5B gene variant inherited from his mother." (PMID 37927187, 2023). "High-throughput sequencing has identified lysine methyl transferase 5B, KMT5B (also known as SUV4-20H1), as a high impact neurodevelopmental disorder risk gene in humans." (PMID 36035149, 2022). "Our findings support the role of de novo missense and nonsense variants in KMT5B-associated GDD/ID, and suggest that this gene should be considered in the differential diagnosis of neurodevelopmental disorders accompanied by macrocephaly and/or overgrowth." (PMID 35433545, 2022). "The association of disease-causing variants in KMT5B with neurodevelopmental disorders, with or without ASD and/or seizures, has only recently been recognized." (PMID 35433545, 2022).
tumor (7 papers, 2015 to 2026). "As a member of histone lysine methyltransferases (KMTs), KMT5B converts H4K20me1 into H4K20me2 and functions in a tumor suppressor-like manner." (PMID 37214395, 2023). "Our study demonstrates a causative role of TRCs and increased R-loop formation for tumor development and identifies Kmt5b as a potent tumor suppressor." (PMID 36376321, 2022). "A preliminary genome-wide screening of candidate genes altered in GBM revealed that the gene encoding the histone methyltransferase KMT5B (alias SUV420H1) is frequently hypermethylated and hypo-hydroxymethylated in this tumor type." (PMID 34447744, 2021). "At the functional level, overexpression KMT5B reduced cell proliferation, cell viability and clonogenic potential in vitro, and tumor growth in vivo in mice xenografts." (PMID 34447744, 2021). "The tumor xenografts thereby revealed that KMT5B overexpression also slows tumorigenesis in vivo, suggesting that KMT5B could play a possible role as a putative tumor suppressor in GBM." (PMID 34447744, 2021). "TRCs in Kmt5b-deficient cells may persistently occur throughout tumor development but may not be required for tumor growth." (PMID 36376321, 2022). "In turn, this may cause global transcriptomic changes, given our finding that overexpression of KMT5B restored H4K20me2 patterns and decreased the expression of several oncogenes, such as IL13RA2, a tumor-restricted receptor." (PMID 34447744, 2021). "KMT5B, also known as SUV4-20H1, is a lysine methyltransferase, catalyzing the generation of H4K20me2 through methylation at the histone H4K20 site, and is increasingly recognized as a pivotal driver of various tumor and non-tumor diseases." (PMID 42080071, 2026).
KMT5B also shares sentences with these, for which no sentence is quoted: breast carcinoma (2 papers); diffuse intrinsic pontine glioma (2); hepatocellular carcinoma (2); Intellectual disability (2); squamous carcinomas (2); acute myeloid leukemia (1); astrocytoma (1); bladder urothelial carcinoma (1); breast-invasive carcinoma (1); chronic myelogenous leukemia (1); Coffin-Siris syndrome (1); coronary heart disease (1); deafness (1); diabetes (1); diffuse astrocytoma (1); epilepsy (1); head and neck cancer (1); kidney diseases (1); Kleefstra syndrome (1); neurodegenerative disease (1); Neurodevelopmental delay (1); oligodendroglioma (1); schizophrenia (1); spinocerebellar ataxia (1); viral infection (1).